RARA (retinoic acid receptor alpha)
Diseases named in the same sentence as RARA in open-access papers (continued):
Sharing a sentence is not in itself a finding about the gene and the disease.
cancer (continued). "The inhibitory effect of RARA could be reversed by overexpression of TXN and PPM1F in both in vivo and in vitro experiments, further highlighting the vital role of inhibiting RARA in the treatment of inducing ferroptosis in cancer." (PMID 38902322, 2024). "At present, there are still few reports on RARα as a cancer factor." (PMID 34858481, 2021). "Previously, it had been exhibited that RARα could bind to E26 transformation-specific-1 (Ets1) promoter and induced the expression of Ets-1 mRNA and protein levels in cancer cells." (PMID 32984354, 2020). "The therapeutic espectrum of berberine also involved the downregulation of Snail, Slug and zinc finger E-box binding homeobox 1 (Zeb1) as well as the regulation of PI3K/Akt and retinoic acid receptor alpha and beta (RARα/RARβ) signaling, acting on the proliferation capacity of various cancer cells." (PMID 31417401, 2019). "The cause and mechanism of abnormal RARα overexpression in malignant tumors have not yet been studied." (PMID 28035062, 2017). "Similarly, in vitro studies, including ours, indicate that functional inhibition of wild type RARA transcriptional activity in mammary epithelial cells changes physiological RA action from morphogenetic to cancer-promoting." (PMID 27894085, 2016). "RARα was involved in the carcinogenesis of several types of cancers." (PMID 27689360, 2016). "Moreover, wild type RARA knock down in the T47D403 context with a RARA-targeting short hairpin RNA (shRNA) (left) significantly counteracts cancer cell growth induced by high ‘supraphysiological’ RA (10-6 M) (right)." (PMID 27894085, 2016). "In this context, stabilizing RARα may permit optimized use of retinoids in cancer prevention and treatment, which warrants further investigation." (PMID 25886043, 2015). "Moreover, circRNAs have also been implicated in the pathogenesis of acute promyelocytic leukaemia (APL), and the most common chromosomal translocation of PML/RARa in patients with APL leads to the abnormal formation of cancer‐specific circRNAs that promote cancer cell survival." (PMID 40099939, 2025). "Among the list of co-expressed features of interest, both RARA (retinoic acid receptor alpha) and RXRA (retinoid X receptor alpha) are identified as strong negative correlates, whereas ZNF207, an early developmental factor linked with pluripotency factors, is a strong positive correlate in cancer." (PMID 37894362, 2023). "All this leads to PML-RARα degradation to restore binding of the wild-type RARα transcription factor to its DNA binding sequence in order to regulate physiological differentiation process within the leukemic cells, as a first-in-class differentiation approach in cancer therapy." (PMID 29921764, 2018). "Therefore, it is possible that stabilizing the RARα protein can optimize this signaling, which indicates that RARα could be a potential target for cancer therapeutics." (PMID 25886043, 2015). "Ligands activated RARα/Sp1-induced monoamine oxidase B (MAO-B), CADM1, E-cadherin and the folate receptor-β gene (FRβ) in cancer cells." (PMID 39858066, 2025). "The correlation between the NCoR1/RARα ratio and CMA score is additionally observed when comparing individual patients in most cancers (Fig. EV7C)." (PMID 40490560, 2025). "The amplification-free, sequencing-based CENAS approach is designed to rapidly detect PML::RARA fusions in APL patients at initial diagnosis, with a high percentage of APL cancer cells (>20%)." (PMID 39766302, 2024). "A high number of genes have RARA putative sequences within themselves, and thus, ATRA treatment enhances the proliferation capacity, resulting in cancer development." (PMID 37645246, 2023). "Antagonism, for most of the selected targets (genes in purple), and agonism, for RARA, RARB, and ADRA2C (genes in red), were proposed as potential approaches for anti‐aging and anti‐cancer treatment." (PMID 37888486, 2023).
cancer (continued). "We then confirmed the computationally predicted differential binding of the top CL1-specific TF, RARα, at chr11:68,043,640–68,043,657 (GRCh38/hg38) in the promoter of TCIRG1, a gene that has a function in bone remodeling and cancer metastasis." (PMID 36266270, 2022). "Seven winning TFs (ETV4, ID2, MEIS1, NR4A3, RARA, TCF3, and ZBTB16) are related to transcriptional misregulation in cancer (p-value: 6.9 × 10−5)." (PMID 36101460, 2022). "We were interested only in the factors whose activity is described as dependent on TGF-β-signaling in cancer cells: EGR125, EGR226, PAX627, RARA and RXRA28, and SP129." (PMID 34239022, 2021). "These sites bind RARA and RXRA in in response to RA-induced differentiation of F9 embryo carcinoma cells." (PMID 34103494, 2021). "ALDH1A1 expression was positively correlated RARα with Ets1 and metalloproteinase 9 (MMP9) was one of the most important substance related to cancer invasion and metastasis." (PMID 32984354, 2020). "We co-transfected kidney epithelial HEK293T cancer cells with GFP-PTEN and PSG5-PML/RARA constructs or with GFP-PTEN and PSG5 control plasmid." (PMID 27626703, 2016). "Among them, several genes were related in cancer pathway such as EGFR, RARA, FGF2, FGFR1, FGFR2, FGFR3, KIT, and CCND1." (PMID 27016420, 2016). "A previous study showed that RARα expression was ubiquitin-dependent and decreased during ATRA-induced neuronal differentiation, which possibly makes cancer cells insensitive to ATRA." (PMID 22087283, 2011). "This hypothesis was derived from the early responses to atRA that were seen in patients with APL before the mechanism of the RARA-PML fusion oncogene was understood, but this hypothesis has since been disproven by clinical data from most cancer types." (PMID 41210994, 2025). "We find that, contrary to expectations, the core component in cancer cells is not limiting but rather is in sufficient excess to accommodate more RARα even in the presence of many other endogenous partner T2NRs." (PMID 39792435, 2025). "Taken together, these data suggest that CIM7 and inhibition of the NCoR1/RARα interaction may have therapeutic potential beyond NSCLC, with broader pan-cancer applications." (PMID 40490560, 2025). "RARA antagonists should not be confused with the subset of atypical retinoids that activate RARA, which are used in cancer research." (PMID 39687864, 2024). "In contrast, no cancer progression-related changes in correlation with RARA transcriptional program was found for ALDH1A3." (PMID 38169509, 2024). "Drug discovery in cancer research has thus far been applied to ALDH1a1, ALDH1a3, and ALDH3a1 while drug discovery in substance abuse has focused on ALDH2, and discovery in the male contraceptive space has focused on ALDH1a1/a2 or RARα." (PMID 39133222, 2024). "Retinoic acid receptor alpha (RARA) and retinoid X receptor alpha (RXRA), which negatively correlate with POLR3G expression across cancers, are retinoid-activated nuclear receptors that mediate transcriptional programs by forming homo- and heterodimers in the presence or absence of specific ligands." (PMID 37894362, 2023). "For these “high‐risk” subjects, preventive strategies such as careful monitoring of electrocardiogram and electrolytes, regular screening of cancer markers, imaging and endoscope, and close detection of the PML::RARα gene should be emphasized to allow early diagnosis and intervention." (PMID 37584196, 2023). "Over the years, ANXA8 has also been found to be upregulated in other cancers, even in the absence of RARA fusion genes." (PMID 32823855, 2020). "Selective RARα agonists have been shown to inhibit proliferation and induce apoptosis of mammary tumour oncogenesis in murine models (MMTV-neu and MMTVwnt1 transgenic mice) relevant to human cancer, and to inhibit LPS-induced B-lymphocyte proliferation." (PMID 33069074, 2020).
cancer (continued). "Selective RARα agonists have been shown to inhibit proliferation and induce apoptosis of mammary tumor oncogenesis in murine models (MMTV-neu and MMTV-wnt1 transgenic mice) relevant to human cancer, and to inhibit LPS-induced B-lymphocyte proliferation." (PMID 29288071, 2018). "Notably, the RXRA protein was in protein complexes with RARA, PPARG, NCOA1, NCOA2, and NCOR2 cancer drivers." (PMID 29572294, 2018). "Moreover, alterations in the expression or activity of specific retinoic acid receptors (RARA, RARB, and RARG) were well-known TFs controlling transcription and inducing diverse types of cancer by recruiting different co-regulator complexes." (PMID 29033978, 2017). "It is noteworthy that CIM7’s selective activity in cancer over normal cells provides a therapeutic window, which may be guided by specific binding to RARα in cancer cells and not in non-tumorigenic cells." (PMID 40490560, 2025). "We also showed that disrupting the specific interaction of NCoR1/RARα leads to selective inhibition of CMA, without contribution of macroautophagy, and that this inhibition of CMA in cancer cells can be attained without major changes to CMA in normal cells." (PMID 40490560, 2025). "Potential off‐target sites that are not gRNA‐based but related to cancer genes were Metazoa‐SRP, RARA, and ACSL6 found in HLA‐A11R hESCs, and PLCG1 found in iC9‐HLA‐A11R hESCs." (PMID 37199039, 2023). "We provide evidence that CIM7 functions via a unique mechanism compared to established RARα agonists and does not affect CMA in non-tumorigenic cells or activate macroautophagy in NSCLC, thus conferring its selectivity for both CMA and as a specific anti-cancer therapeutic." (PMID 40490560, 2025).
infection (11 papers, 2011 to 2025). The state of being infected such as from the introduction of a foreign agent such as serum, vaccine, antigenic substance or organism. "Similar to its effect on CD4+ T cells, RARα has a potent effect on other RAR isoforms in modulating CD8+ T-cell responses following infection." (PMID 30081517, 2018). "With the exception of the experiment exhibiting 100-fold increase in HIV-1 replication, the RARα antagonist was able to inhibit infection to a level similar to that of the mock DC-T co-cultures." (PMID 21738472, 2011). "In female mice, there were 430 DEGs in the infection group (FT) compared with the control group (FC), 195 genes with upregulated expression, such as Ifitm1, Wfdc21, Wfdc17, RARα, and Mgam (P < 0.001), and 235 genes with downregulated expression, such as Xpo7 and Hmbs (P < 0.001)." (PMID 40303139, 2024). "Interestingly, the effects on the trends in the PI3K, p-Akt, and p-Bad expression levels were consistent with the changes in the expression level of RARα after infection of OGD-injured neurons with adenovirus." (PMID 29534734, 2018). "In addition, induction of RARα overexpression by infection with pAd-GFP-RARα further increased the induction of apelin by ATRA." (PMID 29070519, 2017). "Moreover, RARα overexpression introduced by infection of the adenovirus vector pAd-GFP-RARα, further increased the induction of apelin by ATRA." (PMID 29070519, 2017). "GM-2 and GM-3 were predominantly associated with columnar epithelial responses and included regulators such as ATF2, CDX2, FOXJ2, and AHR, with infection-induced up-regulation of TFs such as SPI1, ESRRA, RFX1, and RARA." (PMID 41042872, 2025). "Finally, we did not study if the observed negative effect of RARα on Teff differentiation occurs specifically in TME or broadly in various types of infections." (PMID 40068101, 2025). "However, expression of RARα was decreased in ileum and MLN of VAD sows, suggesting that VA status and infection plays a role in RARα expression and further explaining the impaired innate and adaptive immune responses observed in this study and our previous study." (PMID 37180172, 2023).
hematological malignancies (7 papers, 2011 to 2023). "Obvious differences between APL with FIP1L1::RARA and other hematologic malignancies were identified." (PMID 36776354, 2022). "ACACA, RARA, NOTCH1 and NUP214 are known to form translocations in various types of hematological malignancies while many other fusion genes involve suspected oncogenes, such as RPS6KB1 (RPS6KB1-TMEM49 and RPS6KB1-SNF8), GSDMB (TATDN1-GSDMB) and MCF2L (LAMP1-MCF2L)." (PMID 21247443, 2011).
kidney disease (7 papers, 2011 to 2023). "As such, specific activation of the RARα can be considered a promising therapeutic strategy for patients with renal diseases associated with abnormal proliferation and cellular dedifferentiation." (PMID 22995171, 2012). "In different renal disease models, the association of RARα expression with renal diseases was different." (PMID 23203050, 2012). "The association of RARα expression with renal diseases was also conflicting in different renal diseases." (PMID 23203050, 2012). "There were some reports exploring the association of RARα expression with renal diseases." (PMID 23203050, 2012). "In renal disorder, stimulation of RARα inhibits proliferation and inflammation by inducing podocyte differentiation." (PMID 36768908, 2023). "In kidney disease, the activation of RARα confers renal protection by inducing podocyte differentiation and by inhibiting proliferation and inflammation." (PMID 35237277, 2022). "In a mouse model of HIV-associated nephropathy, Am580 and BD4, water-soluble RARα-specific agonists, protected animals from proteinuria, glomerosclerosis, and podocyte proliferation, and restored podocyte differentiation markers." (PMID 22995171, 2012). "This is consistent with data from the knockout mouse of RARα, which leads to more aggressive kidney disease." (PMID 22995171, 2012). "Activated RARα signaling slows the progression of kidney disease possibly by preserving the quiescent, highly differentiated state of the podocyte." (PMID 22995171, 2012). "Recently, we have shown that the beneficial effects of ATRA for treatment of kidney disease in HIV1 trangenic mice are mediated through the activation of RARα." (PMID 22125642, 2011). "Taken together, these data strongly support using RARα agonists for the treatment of kidney disease." (PMID 22125642, 2011). "Furthermore, RA and RARα agonist have been reported to have beneficial effects in several experimental models of kidney diseases." (PMID 27256691, 2016). "Our data suggest that BD4 is a novel RARα agonist, which could be used as a potential therapy for patients with kidney disease such as HIVAN." (PMID 22125642, 2011). "Based on these findings, we have synthesized a novel RARα agonist, BD4, and characterized its efficacy for the treatment of kidney disease in Tg26 mice." (PMID 22125642, 2011). "Although RA and RARα agonist have been demonstrated to provide protection in several experimental models of kidney disease, there are very few studies to report the change of STRA6/CRBP1 cascades in kidney diseases." (PMID 27256691, 2016).
hematologic cancer (4 papers, 2014 to 2025). "It is a highly aggressive hematopoietic neoplasm that is associated with rearrangements between the genes encoding retinoic acid receptor alpha (RARα) or other members of the retinoic acid receptor (RAR) family and several partner genes." (PMID 33287098, 2020).
neurodegenerative disease (3 papers, 2009 to 2022). A disorder of the central nervous system characterized by gradual and progressive loss of neural tissue and neurologic function. "The nuclear receptors (NRs) RARα, RXRα, PPARα, and PPARγ represent promising pharmacological targets for the treatment of neurodegenerative diseases." (PMID 30759808, 2019). "RARα also represents a promising potential therapeutic target in neurodegenerative diseases." (PMID 35237277, 2022). "Recently, it has also been shown that the stimulation of RARα, RXRα, and PPARα/γ may be beneficial in treating neurodegenerative diseases." (PMID 30759808, 2019). "Altogether, the ability of RAR and PPAR stimulation to affect Aβ accumulation suggests that compounds with broad agonist activity toward RARα, RXRα, and PPAR-α and -γ could represent useful pharmacological tools to provide novel inroads for the treatment of neurodegenerative diseases." (PMID 30759808, 2019).
cardiovascular disease (2 papers, 2013 to 2020). "Some of the master regulators identified in WAT in the present study (Jun, Fos, Rarα, Pparα, Stat1, Stat5, Sp1) were also reported to control liver lipid metabolism and/or the inflammatory responses of the liver in experimental diet-induced cardiovascular disease." (PMID 24086498, 2013).
colorectal (2 papers, 2010 to 2020). "Although other retinoic receptors including retinoic acid receptor alpha (RAR alpha), RAR beta, RXR beta and RXR gamma were expressed in mouse adeoma, downregulation of RXR alpha appears to be an early event in colorectal carcinogenesis and independent of the expression of beta-catenin." (PMID 24281088, 2010).
metabolic disease (2 papers, 2017 to 2020). A congenital disorder (due to inherited enzyme abnormality) or acquired (due to failure of a metabolically important organ) disorder resulting from an abnormal metabolic process. "Therefore, downregulation of ApoC-III by selective RARα activation may lead to multiple beneficial effects in terms of metabolic disease without the unwanted side effects." (PMID 28724938, 2017).
inflammation (1 paper, 2022). Aberrant reaction of the microcirculation characterized by movement of fluid and leukocytes from the blood into extravascular tissues. "A more recent study reported that RARα signaling enhances Tfh differentiation in an airway inflammation mouse model, perhaps through inhibiting IL2Rα upregulation on T cells, as IL2R signaling inhibits Tfh differentiation by repressing BCL6." (PMID 35359939, 2022).
RARA also shares sentences with these, for which no sentence is quoted: Disseminated intravascular coagulation (4 papers); acute lymphoblastic leukemia (3); adenocarcinoma (2); anaplastic large cell lymphoma (2); B cell lymphomas (2); Coagulopathy (2); Crohn disease (2); glioblastoma (2); Glucose intolerance (2); intracranial hemorrhage (2); lymphoid cancer (2); medulloblastoma (2); monocytic leukemia (2); phyllodes tumor (2); sarcoma (2); stomach cancer (2); T-cell acute lymphoblastic leukemia (2); -dependent (1); acute intermittent porphyria (1); acute monoblastic leukemia (1); adenoma (1); adenosarcoma (1); adult T-cell lymphoma (1); Anxiety (1); Aortic dissection (1); Arthritis (1); autoimmune disease (1); bladder cancer (1); bladder tumour (1); cardiomyopathy (1).
A further 68 diseases each share a sentence with RARA in 1 paper.